H19 (H19 imprinted maternally expressed transcript)
Diseases named in the same sentence as H19 in open-access papers (continued):
Sharing a sentence is not in itself a finding about the gene and the disease.
hepatocellular carcinoma (continued). "Among these, Air, Hotair, LincRNA-ROR, Hulc, and H19 have already been identified as positively correlated with hepatocellular carcinoma." (PMID 26272696, 2015). "Epigenetic activation of the MiR-200 family contributes to H19-mediated metastasis suppression in hepatocellular carcinoma." (PMID 26376677, 2015). "We previously reported an increased expression of H19 in hepatocellular carcinoma with higher JNK1 activation." (PMID 23965803, 2013). "H19, an imprinted gene that displays maternal monoallelic expression during development and is reactivated during adult tissue regeneration and hepatocellular carcinoma was induced." (PMID 21779369, 2011). "In hepatoma cells, H19 promotes autophagy by inhibiting the PI3K–Akt–mTOR pathway." (PMID 38355574, 2024). "Epigenetic activation of the miR-200 family in hepatocellular carcinoma has been shown to prevent H19-mediated metastasis, indicating that H19 may have tumor-suppressive activity." (PMID 38836981, 2024). "From other point, it has been discussed that H19 may promote gene GST-π expression in hepatocellular carcinoma." (PMID 36246634, 2022). "MiR-200 family was found to be sponged by H19 in several cancers, such as hepatocellular carcinoma." (PMID 36246634, 2022). "For example, the lncRNA H19, induced during the development of the liver in mice, was highly expressed in hepatocellular carcinoma (HCC) tissues and could induce drug resistance in HCC." (PMID 34820419, 2021). "Mechanically, H19 regulates the methylation of the promoter of multidrug resistance 1 (MDR1) gene, thereby inducing the expression of the product p-glycoprotein (encoded by MDR1) and MDR1-related drug resistance in human hepatocellular carcinoma HepG2 cells." (PMID 34199840, 2021). "Similarly, H19 has been found to sponge miR-3126-5p to allow the expression of ERβ receptor in papillary thyroid carcinoma, but also to sponge miR-193b in hepatocellular carcinoma, leading to the activation of MAPK1 and other oncogenes." (PMID 33291403, 2020). "We previously reported a positive correlation between increased H19 expression and HNF4α promoter hypomethylation in human hepatoma cells and in livers of multiple mouse models, including fasting, high fat diet (HFD)-induced T2D, and liver-specific H19 overexpression." (PMID 31953394, 2020). "Exosomal lncRNA H19 may be a new therapeutic target to reduce the recurrence and metastasis of hepatocellular carcinoma." (PMID 33401249, 2020). "Furthermore, we provide a landscape of NSUN2-mediated m5C modification in hepatocellular carcinoma cells, and identified H19 lncRNA as a target of NSUN2." (PMID 32978516, 2020). "Downregulating the expression of lncRNA H19 lowers the cellular drug accumulation level in human hepatocellular carcinoma (HCC) by enhancing the methylation of the multidrug resistant gene 1 (MDR1) promoter and upregulating p-glycoprotein expression, which ultimately leads to doxorubicin resistance." (PMID 31777598, 2019). "In hepatocellular carcinoma, H19 was shown to act as a tumor suppressor." (PMID 29561759, 2018). "H19 also plays a major role in disease progression, particularly in hepatocellular carcinoma." (PMID 28933364, 2017). "Conversely, H19 may also possess tumor suppression properties, and epigenetic activation of the miR-200 family contributes to H19-mediated metastasis suppression in hepatocellular carcinoma." (PMID 27487126, 2017). "In conclusion, H19 suppresses hepatocarcinogenesis, hepatoma cell growth, and HCC chemoresistance." (PMID 31225433, 2017).
hepatocellular carcinoma (continued). "Thus, the colony formation assay - a well established method to determine every cell’s ability to undergo unlimited division in a cell population 22 - was performed in three different stably H19 overexpressing human hepatoma cell lines." (PMID 31225433, 2017). "Notably, the lncRNAs HOTTIP, H19, HOTAIR, MALAT1, antisense Igf2r (AIR), HOXA13, GTL2 (also called MEG3) and uc002mb have been reported in association with hepatocellular carcinoma (HCC)." (PMID 26172293, 2015). "Their results suggested that H19 might be used for histopathological and cytological diagnosis of hepatocellular carcinoma." (PMID 24757675, 2014). "Overexpression of H19 was found in hepatocellular carcinoma." (PMID 24757675, 2014). "These cells highly expressed Afp, H19, and Ahsg, which were essential factors for hepatocyte differentiation and tumorigenesis in hepatocellular carcinoma (HCC)." (PMID 35465320, 2022). "Furthermore, H19 may be involved in epithelial to mesenchymal transition and promotes invasion and metastasis of some solids cancers such as pancreatic cancer and hepatocellular carcinoma 38-43." (PMID 31772651, 2019). "Furthermore, H19’s normal regulation is disturbed in diseases, such as hepatocellular carcinoma." (PMID 28933364, 2017). "We will discuss dysregulation of H19 in the progression of liver-related diseases, including steatosis, fibrosis, cirrhosis, diabetes, and hepatocellular carcinoma (HCC) with a particular focus on the epithelial to mesenchymal transition (EMT)." (PMID 28933364, 2017). "Upregulation of H19 and Igf2 expression has been shown in HBV-associated HCC and an imbalance in H19 and Igf2 expression associated with hepatocellular carcinoma progression." (PMID 25861629, 2015). "Moreover, we suggest the lncRNA H19 as a putative therapeutic target in hepatocellular carcinoma." (PMID 26272696, 2015). "Likewise, ectopic H19 expression enhances the tumorigenic potential of hepatocellular carcinoma cells in vivo, suggesting that H19 may have oncogenic properties in these types of cancers." (PMID 24810858, 2014). "A study investigated the relationship between the lncRNAs HOTTIP, H19, and HOTAIR and miRNA 152, as well as the role of these interactions in the progression of HCV-induced liver lesions to hepatocellular carcinoma." (PMID 41465470, 2025). "In hepatocellular carcinoma (HCC), both the H19 lncRNA and m5C methylation are increased, which is significantly related to m5C-induced H19 lncRNA expression and is uniquely connected to the Ras-GTPase-activating protein SH3 domain-binding protein 1 (G3BP1)." (PMID 38871819, 2024). "reveled that NSUN2, an m5C methyltransferase, is significantly upregulated in hepatocellular carcinoma (HCC), and it promotes tumor progression by catalyzing the H19 lncRNA methylation-mediated recruitment of the G3BP1 oncoprotein." (PMID 36777349, 2023). "The “writer” NSUN2 modifies the lncRNA H19 and recruits the oncoprotein G3BP1 in hepatocellular carcinoma, suggesting that m5C modifications are involved in malignant tumor progression." (PMID 37666951, 2023). "Previous studies revealed that the lncRNAs H19 and NEAT1 were found to directly target miR-193a-3p in Hepatocellular Carcinoma and Lung Adenocarcinoma, respectively." (PMID 36873948, 2023). "In hepatocellular carcinoma, NSUN2 methylates and increases the stability of the tumor-related lncRNA H19. m5C-methylated H19 correlates to poor hepatocellular carcinoma differentiation." (PMID 36969033, 2023). "We found that H19 was specifically bound by EZH2 and JARID2 in hepatoma cell lines and repressed in HCC patients." (PMID 36578923, 2022). "In hepatocellular carcinoma, NSUN2 expression is increased, and H19 lncRNA stability is maintained to promote cancer development." (PMID 35433474, 2022).
hepatocellular carcinoma (continued). "In hepatocellular carcinoma, NSUN2 affects the biological function of hepatocellular carcinoma cells and methylates lncRNA H19RNA and methylated H19 recruits oncogene G3BP1 to promote the occurrence and development of tumors." (PMID 35574373, 2022). "In hepatocellular carcinoma (HCC), m5C-related RNA methyltransferase NSUN2 targets lncRNA H19 and stabilizes its expression." (PMID 34777473, 2021). "Emerging evidence shows that expression of H19 is upregulated in many cancers, including CRC, hepatocellular carcinoma, esophageal cancer, ovarian cancer, breast cancer and bladder cancer, with or without the loss of imprinting." (PMID 26989025, 2016). "Here, it has been demonstrated that CD90+ hepatocellular cancer cells derived from the Huh7 cell line secrete exosomes containing different types of lncRNAs, including HOTAIR, HULC, linc-ROR and H19." (PMID 26516918, 2015). "For instance, H19 is thought to induce p-glycoprotein expression and by regulating the methylation of MDR1 promoter with the effect that drug resistance is promoted in hepatocellular carcinoma cells." (PMID 36188624, 2022). "At the relatively low dose we used, we found no signs of tumors, as assessed in multiple tissue section micrographs and by the undetectable levels of the typical markers of hepatocellular carcinoma Afp and H19 (data not shown)." (PMID 28874443, 2017). "H19 interaction with the miRNA let-7 and MYC is well known for tumor progression, however, recently microarray-based study has surfaced the interplay between H19 and β-catenin, that triggers growth in Hepatocellular carcinoma via up-regulation of the CDK8 expression." (PMID 32699525, 2020). "Three lncRNAs, H19, HOTAIR and lncRNA highly upregulated in liver cancer (HULC), were found overexpression in human hepatocellular carcinomas (HCC)." (PMID 24063685, 2013). "Besides, MBD1 (Methyl-CpG–Binding Domain Protein 1), the partner protein of H19, can induce methylation at H3K9me3 (lysine 9 of histone H3) to differentially methylated regions (DMRs) of correlated imprinted genes like IGF2, SLC38A4 (tumor suppressor in hepatocellular carcinoma) and PEG1." (PMID 36246634, 2022). "LncRNA H19 was previously reported to be oncogenic in glioma, hepatocellular carcinoma (HCC) and bladder cancer, but none of them were related to cancer metabolism 71-74." (PMID 32174794, 2020).
ovarian carcinoma (80 papers, 2009 to 2025). A malignant neoplasm originating from the surface ovarian epithelium. "Further, several lncRNAs have been linked with p-53 in ovarian cancer, of which H19, MALAT1, PVT1 and LINC-ROR are upregulated while MEG3 and PANDA are known to be downregulated." (PMID 39912983, 2025). "Overexpression of H19 has been linked to the cisplatin resistance and migration of ovarian cancer during EMT." (PMID 34250088, 2021). "The frequent loss of H19 imprinting has been detected in ovarian cancer tissues, especially in malignant serous cystadenocarcinomas." (PMID 27664137, 2017). "We have shown that IGF2 overexpression in ovarian cancer is associated with hypermethylation of CTCF binding sites within the IGF2/H19 imprint center." (PMID 23745176, 2013). "The abnormal expression of LncRNA H19 and miR-140-5p has been linked to ovarian cancer (OC)." (PMID 34250088, 2021). "Although the abnormal expression of LncRNA H19 and miR-140-5p has been linked to ovarian cancer, whether H19 directly regulates miR-140-5p in ovarian cancer cells has been unclear." (PMID 34250088, 2021). "In patients with epithelial ovarian cancer, loss of heterozygosity of both Igf2 and H19 genes tend to be found in advanced clinical stages of ovarian cancer, loss of imprinting of Igf2 and H19 genes may be contributed to the development of ovarian cancer." (PMID 29921308, 2018). "Cationic polymer PEI based delivery of DTA-H19 plasmid, encoding the toxic DT‐A transcriptionally controlled by regulatory sequences of the H19 gene, showed high killing potential in ovarian cancer cell lines and a significant tumor growth inhibition in animals." (PMID 22069564, 2010). "The treatment of ovarian cancer cells with a plasmid expressing the diphtheria toxin gene under the control of the lncRNA H19 promoter produced anti-cancer effect with adequate safety." (PMID 39912983, 2025). "Ginsenoside 20 (S) -Rg3, found in red ginseng, was shown to supress the Warburg effect in ovarian cancer cells by modulating the lncRNA H19/miR-324-5p/PKM2 pathway as well as downregulating a total of 67 lncRNAs impacting various cellular processes." (PMID 39912983, 2025). "In ovarian cancer, H19 promotes tumor growth, metastasis, and chemoresistance through modulation of key signaling pathways and interaction with microRNAs." (PMID 38166752, 2024). "H19 has been found to play a role in the development of ovarian cancer by regulating various pathways, as evidenced by increased expression levels in cisplatin-resistant A2780-DR cells." (PMID 38166752, 2024). "On the other hand, H19 expression was shown to be considerably higher in the cisplatin-resistant ovarian cancer cell line OVCAR3/DDP than in the OVCAR3 cell line." (PMID 39337410, 2024). "LncRNA H19 is believed to play an important role in the development of ovarian cancer by regulating various pathways, as evidenced by increased expression levels in cisplatin-resistant A2780-DR cells." (PMID 39337410, 2024). "In ovarian cancer, for instance, H19 has been found to play a role in promoting cell proliferation, invasion capability, and drug resistance." (PMID 38166752, 2024). "In ovarian cancer, H19 regulates the Warburg effect by directly binding to miR-324-5p and upregulating PKM2, a target of miR-324-5p, thereby enhancing glycolysis metabolism." (PMID 38166752, 2024). "It has been shown that MF reduces the motility and invasiveness of both endometrial and ovarian cancer cells partly due to the decreasing synthesis of H19 RNA." (PMID 39273414, 2024). "In SKOV3 and A2780 cells treated with ginsenoside 20(S)-Rg3, H19 overexpression in ovarian cancer raised glucose consumption, lactate production, and PKM2 expression." (PMID 37821504, 2023). "An interesting study reported that lncRNA H19 levels were significantly increased in cisplatin-resistant A2780/CDDP ovarian cancer cells and in patients with high-grade serous ovarian cancer (HGSC)." (PMID 37175546, 2023).
ovarian carcinoma (continued). "Several lines of research have demonstrated that NRF2 signalling can be indirectly modulated by non-coding RNA, such as miR-181d and Lin-H19, and that these can modulate drug response in ovarian cancer." (PMID 35453348, 2022). "Recently, it was shown that the expression of H19 was enhanced in cisplatin-resistant ovarian cancer cells." (PMID 36246634, 2022). "Controlled by H19, the RNA present in ovarian cancer cells at high dose and almost undetectable in adjacent normal cells resulted in a 40% inhibition of the growth of ectopically developed tumors." (PMID 35744957, 2022). "It has been shown that hypermethylation of CTCF-binding site at the H19/ICR increased expression of IGF2 in ovarian cancer." (PMID 35459174, 2022). "The expression of the DT gene controlled by H19 regulatory sequences was chosen as another possible approach to combat ovarian cancer." (PMID 35744957, 2022). "Ectopic expression of H19 promotes cell proliferation while silencing the expression of H19 by RNA interference inhibits the growth of ovarian cancer cells and induces cell cycle arrest and apoptosis." (PMID 35103065, 2022). "H19 can confer cisplatin resistance to ovarian cancer cells via regulating glutathione metabolism in vitro and in vivo." (PMID 36246634, 2022). "While its expression is downregulated after birth, the expression of H19 is significantly upregulated in endometrial carcinoma and ovarian cancer." (PMID 35103065, 2022). "It was observed that lncRNA H19 overexpression in ginsenoside 20(S)-Rg3-treated ovarian cancer cells enhances glucose consumption, lactate production and PKM2 expression." (PMID 33652661, 2021). "To further study the relationship between H19 and miR-140-5p on OC, we analyzed the expression of H19 and miR-140-5p in several ovarian cancer cell lines." (PMID 34250088, 2021). "In ovarian cancer, H19 overexpression has been observed in 12 of 16 patients and ovarian cancer cell lines, including OVCAR-3, SKOV-3, and OV-90." (PMID 35011637, 2021). "Increasing findings indicate that lncRNA H19 plays an important role in chemotherapy drug resistance of ovarian cancer." (PMID 34512721, 2021). "In this study, we deeply explored the relationship between H19 and miR-140-5p in ovarian cancer and the mechanism of action in regulating OC progression." (PMID 34250088, 2021). "We found that overexpression of H19 in ovarian cancer cells downregulated miR-140-5p and promoted invasion, migration, and epithelial-mesenchymal transition of ovarian cancer cells by the activation of the PI3K/AKT signaling pathway." (PMID 34250088, 2021). "In the OVCAR3/DDP resistant ovarian cancer cell, silencing lncRNA H19 can significantly increase E-cadherin expression and reduce twist, slug, and snail expression, indicating that lncRNA H19 induces cisplatin resistance via EMT." (PMID 34512721, 2021). "LncRNA H19 enhances TGF-β-activated epithelial-mesenchymal transition (EMT) in ovarian cancer through serving as a ceRNA of miR-370-3p." (PMID 31703640, 2019). "H19 has been investigated as a targeted therapy strategy for ovarian cancer and its inhibition suppresses tumor growth." (PMID 31379598, 2019). "H19 expression was showed to be regulated by DNA methylation, methylation of H19 contributed to ovarian cancer inhibition." (PMID 29921308, 2018). "This pioneering study is the first in the ovarian cancer ascites fluid to demonstrate the therapeutic potential of modulating H19 in vivo." (PMID 29921308, 2018). "Lately, six lncRNAs RUNX1-IT1, MALAT1, H19, HOTAIRM1, LOC100190986 and AL132709.8 were validated to be associated with recurrence of ovarian cancer through using the microarray data preprocessing." (PMID 29921308, 2018). "For example, metformin and histone H1.3 inhibited ovarian cancer cell migration and invasion by down-regulating H19 via DNA methylation." (PMID 29921308, 2018). "For example, aberrant expression of the lncRNA H19 occurs in ovarian cancer and other types of cancers." (PMID 30374364, 2018).